RBM17 (RNA binding motif protein 17)
Description:
Splice factor that binds to the single-stranded 3'AG at the exon/intron border and promotes its utilization in the second catalytic step. Involved in the regulation of alternative splicing and the utilization of cryptic splice sites. Promotes the utilization of a cryptic splice site created by the beta-110 mutation in the HBB gene. The resulting frameshift leads to sickle cell anemia.
Synonyms: SPF45; MGC14439
Tractability: Small molecule: a structure with a bound ligand is known; a high-quality ligand is known. PROTAC: UniProt records ubiquitination sites on it; ubiquitination databases record sites on it; its protein half-life has been measured; a small molecule that binds it is known.
Target class: Other nuclear protein
Gene: Protein-coding gene on chromosome 10 (6,086,898 to 6,117,457, forward strand). Ensembl gene ENSG00000134453.
Subcellular location: Nucleus
Subcellular location (Human Protein Atlas): Nucleoplasm
Pathways (Reactome):
Metabolism of RNA: mRNA Polyadenylation; mRNA Splicing - Major Pathway
Chromatin organization: CHD1 and CHD2 subfamily
Disease: Dengue Virus-Host Interactions
Gene Ontology:
Molecular function: protein binding; nucleic acid binding; RNA binding
Biological process: alternative mRNA splicing, via spliceosome; mRNA cis splicing, via spliceosome; RNA splicing, via transesterification reactions
Cellular component: nucleoplasm; nucleus; protein-containing complex
Genetic constraint (gnomAD): Loss-of-function variants: 1 observed, 31.37 expected, observed/expected ratio (o/e) 0.0319, 90% interval 0.01 to 0.15. The upper end of that interval is the gene's LOEUF score, 0.15, which puts it in group 1 of 6, group 1 being the genes least tolerant of losing a copy. Missense variants: 170 observed, 333.24 expected, observed/expected ratio (o/e) 0.51, 90% interval 0.45 to 0.58. Synonymous variants: 112 observed, 122.67 expected, observed/expected ratio (o/e) 0.91, 90% interval 0.78 to 1.07.
Homologues: Orthologues: chimpanzee RBM17 (100% identical), macaque RBM17 (100% identical), dog RBM17 (99% identical), pig RBM17 (99% identical), rat Rbm17 (99% identical), mouse Rbm17 (99% identical), guinea pig RBM17 (96% identical), tropical clawed frog rbm17 (85% identical), zebrafish rbm17 (82% identical), Drosophila melanogaster Spf45 (38% identical), Caenorhabditis elegans rbm-17 (25% identical).